CDKN2A (cyclin dependent kinase inhibitor 2A)
Diseases named in the same sentence as CDKN2A in open-access papers (continued):
Sharing a sentence is not in itself a finding about the gene and the disease.
oligodendroglioma (55 papers, 2003 to 2026). A well-differentiated (WHO grade II), diffusely infiltrating neuroglial tumor, typically located in the cerebral hemispheres. "Co-deletion of chromosomes 1p and 19q was first reported in the same period as the deletion of CDKN2A/B and has since become an essential molecular feature in the diagnosis of oligodendroglioma, following the discovery of IDH mutations." (PMID 38473369, 2024). "Less than 10% of CNS WHO grade 3 IDH-mutant and 1p/19-codeleted oligodendrogliomas show homozygous CDKN2A/B deletion, associated with worse outcome and shorter overall survival." (PMID 37138345, 2023). "While 1p/19q co-deletion and IDH mutation occur in the early stages of oligodendroglioma formation, progression to a higher grade is associated with homozygous deletion of CDKN2A/B." (PMID 37138345, 2023). "Only 5 of 27 (19%) cases of IDH-mutant cases had loss of CDKN2A detected and 0 of 13 cases of oligodendroglioma had a loss in CDKN2A, although one case demonstrated a frame-shift deletion alteration." (PMID 36397144, 2022). "The cnLOH at 9p was previously observed in oligodendroglioma and was associated with loss of CDKN2A expression in approximately 30% of the cases examined." (PMID 31217899, 2019). "Required for oligodendroglioma diagnosis; rare cases with CDKN2A/B loss have worse prognosis." (PMID 41346390, 2025). "CDKN2A homozygous loss is associated with adverse prognosis in grade 3 oligodendroglioma." (PMID 40949165, 2025). "For example, S100 glial precursor promoter-regulated v-ERBB (an activated member of the EGFR family) transgenic mice develop oligodendrogliomas, which are potentiated in terms of shorter latency and increased malignancy when initiated in mice deficient for both p16 and p19 (Cdkn2a-null mice)." (PMID 29052807, 2017). "A rare finding in oligodendrogliomas, CDKN2A/B is the sole molecular marker to distinguish grade 2 from grade 3 oligodendrogliomas but was not present in our patient’s tumor." (PMID 39857783, 2025). "The diagnosis was grade 2 IDH1 R132H mutant, 1p/19q codeleted oligodendroglioma with the following histomolecular characteristics: Ki‐67 < 5%, absence of mitoses, necrosis, or microvascular proliferations, pTERT mutant, and CDKN2A/B intact." (PMID 40956046, 2025). "In oligodendrogliomas, CDKN2A HD was detected in 7.04% (5/71) of tumors; all were WHO CNS grade 3 tumors." (PMID 38109891, 2024). "The prognostic relevance of CDKN2A/B deletions for patients with genetically defined oligodendrogliomas is currently less well established." (PMID 34967922, 2022). "In future studies, however, the existence of oligosarcomas as a distinct group of IDH-mutant tumors with frequent deletions of 1p/19q as well as CDKN2A/B should be considered in order to exclude an admixture with conventional oligodendrogliomas." (PMID 34967922, 2022). "We hypothesize that high expression of HIP1R and CDKN2A represents the most indolent oligodendrogliomas, which have a favorable prognosis." (PMID 40264576, 2025). "Furthermore, LMC-based grading reflected changes of copy number, in that it stratified oligodendrogliomas according to present copy number variations in addition to 1p/19q-codeletion as well as homozygous deletion of CDKN2A/B." (PMID 40849395, 2025). "STS in the predominantly LTS cluster B comprised three cases with oligodendroglioma (CNS WHO grade 3), of whom one displayed a CNV profile suggesting complete loss of chromosome 9 (including the locus for CDKN2A/B), while another tumor harbored losses in chromosomes 14q, 15q, and gain in 11q." (PMID 39954095, 2025). "Similarly, low protein expression levels of p16 (CDKN2A) were also predictive of poorer patient survival in oligodendrogliomas, reported over two decades ago." (PMID 39578301, 2025). "The role of CDKN2A deletion in patients with oligodendroglioma remains under investigation." (PMID 39876890, 2024).
oligodendroglioma (continued). "For instance, homozygous deletion involving the CDKN2A locus found in adult WHO Grade 3 oligodendrogliomas has been linked to lower survival, regardless of microvascular proliferation with or without necrosis." (PMID 39108689, 2024). "Since CDKN2A loss is not seen in low-grade IDH-mutant oligodendrogliomas, detection of this molecular alteration can be used to distinguish between grade 2 and grade 3 tumors when histology is equivocal." (PMID 37138345, 2023). "Additionally, in oligodendrogliomas of histopathological unclear grade, it is recommended to evaluate the CDKN2A/B status and to use homozygous deletion as reason to assign grade 3." (PMID 34967922, 2022). "However, no variant or amplification was found in PDGFRα on 4q, a gene involved in the development of human oligodendroglioma, or in CDKN2A on 9p, one of the most frequently altered genes in diverse cancer types." (PMID 31217899, 2019). "Moreover, different MLPA kits have been successfully used for this type of analysis, e.g., Kit P088 and P105 for the analysis of Oligodendrogliomas, P024 for CDKN2A/B and P036 for subtelomeric regions." (PMID 20113482, 2010). "Loss of chromosomal regions on 1p and 19q is characteristic of oligodendrogliomas, but there is also evidence for another subset of oligodendrogliomas that have amplification of EGFR oncogene, loss of heterozygosity on chromosome 10 and homozygous deletion of the CDKN2A tumor suppressor gene." (PMID 18173856, 2008). "However, the effect of CDKN2A/B deletion in oligodendroglioma is less clear." (PMID 39876890, 2024). "CDKN2A homozygous deletion predicted worse outcomes in the overall patient population, particularly in IDH-mutant 1p/19q oligodendrogliomas (grade 3)." (PMID 36900302, 2023). "Additionally, there is evidence that homozygous loss of CDKN2A may also be a negative prognostic indicator in oligodendrogliomas." (PMID 36397144, 2022). "In oligodendrogliomas, CDKN2A/B HD, which is not seen in WHO CNS grade 2 tumors but can be seen in some grade 3 tumors, has been found to be related to short survival times independent of MVP and necrosis." (PMID 38109891, 2024). "CDKN2A homozygous deletions were not tested because fewer than 1% (1/171) of TCGA oligodendrogliomas harbored these alterations." (PMID 39259414, 2024). "The CNS WHO grading biomarker CDKN2A/B homozygous deletion was detected in 11 IDH-mutant astrocytic gliomas (two primary tumors and 9 recurrences) and one recurrent oligodendroglioma, and hence the tumors were designated as CNS WHO grade 4 and 3, respectively as indicated." (PMID 36739454, 2023). "Of note, in two cases of oligosarcomas presenting with heterozygous deletion of CDKN2A/B this was not present in the primary oligodendroglioma." (PMID 34967922, 2022). "Oligo Cdkn2a tumors represent the first mouse model system to recapitulate the genetic, histological and transcriptional features of human IDH-mutant 1p/19q-codeleted oligodendrogliomas, offering a platform to further dissect tumor biology and test new therapeutic strategies." (PMID 42239081, 2026). "It is intriguing that LMC-based grading separated the oligodendrogliomas according to homo- but not heterozygous CDKN2A/B deletion status, except for a single grade 2 tumor not meeting any malignancy criterium besides the homozygous CDKN2A/B deletion." (PMID 40849395, 2025). "No CDKN2A heterozygous deletion or amplification was detected in oligodendrogliomas." (PMID 38109891, 2024). "In the oligodendrogliomas, none of the WHO CNS grade 2 tumors had CDKN2A HD, while 5 (11.6%) of 43 grade 3 cases showed CDKN2A HD." (PMID 38109891, 2024).
oligodendroglioma (continued). "While CDKN2A/B HD can be seen in some (<10%) of WHO CNS grade 3 oligodendrogliomas, it is not expected in grade 2 oligodendrogliomas, and its presence has been related to short survival times independent of MVP and necrosis." (PMID 38109891, 2024). "Several previous studies that aimed to identify prognostic indicators of oligodendroglioma proposed the use of CDKN2A/B, PTEN, NOTCH1, and other biomarkers as classification criteria to reclassify oligodendroglioma, but there is no consistent conclusion." (PMID 36588901, 2022).
acute lymphoblastic leukemia (48 papers, 2004 to 2025). Leukemia with an acute onset, characterized by the presence of lymphoblasts in the bone marrow and the peripheral blood. "This investigation was undertaken to examine the correlation between CDKN2A polymorphisms and the risk of acute lymphoblastic leukemia in children." (PMID 39443269, 2024). "A genome-wide analysis demonstrated that a common variation at 9p21.3 (intron 1 of CDKN2A) influences the risk of childhood acute lymphoblastic leukemia." (PMID 26720758, 2015). "In addition, it has been shown that CDKN2A loss can contribute towards resistance to targeted therapy in acute lymphoblastic leukemia induced by BCR-ABL translocation." (PMID 21423728, 2011). "Currently, the significance of CDKN2A/B mutations in the pathogenesis and prognosis of acute lymphoblastic leukemia (ALL) is inconclusive." (PMID 37314514, 2023). "Interestingly, the role of CDKN2A/B alterations in CCA is consistent with those found in other onco-hematologic settings, such as acute lymphoblastic leukemia, where CDKN2A/B mutations have been highlighted as independent poor prognostic markers and then included in the risk stratification." (PMID 36335135, 2022). "Two of the hallmarks of T-cell acute lymphoblastic leukemia (T-ALL) are aberrant Notch signaling and loss of the CDKN2A locus." (PMID 33445626, 2021). "Furthermore, somatic CDKN2A gene mutations have been found in some people with brain tumors and in children with acute lymphoblastic leukemia (From this point of view, VERO cells could be considered a cancer-prone cell model." (PMID 33167404, 2020). "Cyclin-dependent kinase inhibitor 2A/B (CDKN2A/B) genes at chromosomal arm 9p21 are frequently altered in patients with acute lymphoblastic leukemia (ALL)." (PMID 36601176, 2023). "The common missense variant at CDKN2A (rs3731249) was found in two WHO°I IVM samples, which has been shown to be associated with increased susceptibility to acute lymphoblastic leukemia." (PMID 31470906, 2019). "We verified this hypothesis by comparing murine and human AML cell lines with high or low expressions of p16INK4A and/or p18INK4C and murine Cdkn2a−/− vs. Cdkn2a+/+ BCR-ABLp185+ cells modelling acute lymphoblastic leukaemia (ALL)." (PMID 35326705, 2022). "Although illegitimate V(D)J recombination may be responsible for creating CDKN2A deletions in acute lymphoblastic leukemia, more breakpoint sequence data will be needed for other types of cancers to delineate the molecular mechanisms." (PMID 17440616, 2007). "This study aimed to explore the correlation between the deletion of the CDKN2A/B gene and the prognosis of pediatric acute lymphoblastic leukemia (ALL) patients." (PMID 40017529, 2025). "Optical Genome Mapping (OGM) enables high-resolution detection of structural genomic alterations with established prognostic significance in acute lymphoblastic leukemia (ALL), including deletions affecting CDKN2A/B, IKZF1, and PAX5 loci." (PMID 41228238, 2025). "Cyclin-dependent kinase inhibitor 2A/B (CDKN2A/B) genes are frequently altered in acute lymphoblastic leukemia (ALL) patients." (PMID 39408811, 2024). "Pediatric B-cell precursor acute lymphoblastic leukemia (BCP-ALL) is associated with a high frequency of copy number alterations (CNAs) in IKZF1, EBF1, PAX5, CDKN2A/B, RB1, BTG1, ETV6, and/or the PAR1 region (henceforth: B-cell development genes)." (PMID 30874617, 2019). "Recurrent deletions of the CDKN2A/ARF/CDKN2B genes encoded at chromosome 9p21 have been described in both pediatric and adult acute lymphoblastic leukemia (ALL), but their prognostic value remains controversial, with limited data on adult T-ALL." (PMID 30041662, 2018). "Acute lymphoblastic leukemia (ALL) is the most common cancer in children, and alterations in CDKN2A were considered to play an important role on leukemogenesis." (PMID 29654170, 2018).
acute lymphoblastic leukemia (continued). "The locus CDKN2A/B (9p21.3), which comprises the tumor suppressors genes CDKN2A and CDKN2B and the long noncoding RNA (lncRNA) known as ANRIL (or CDKN2B-AS), was associated with childhood acute lymphoblastic leukemia (ALL) susceptibility in several genome wide association studies (GWAS)." (PMID 28481918, 2017). "MYC-translocated T-lineage acute lymphoblastic leukemia (T-ALL) is a rare subgroup of T-ALL associated with CDKN2A/B deletions, PTEN inactivation, and absence of NOTCH1 or FBXW7 mutations." (PMID 30304769, 2018). "A recently characterized high-risk subgroup in acute lymphoblastic leukemia (ALL) is defined by the IKZF1plus profile, which is marked by the co-occurrence of IKZF1 deletions alongside deletions in CDKN2A/B, PAX5, or the PAR1 region, in the absence of ERG gene alterations." (PMID 41228238, 2025). "It is important to note that the prognostic significance of homozygous CDKN2A/CDKN2B deletions is limited to cortical and mature T-cell acute lymphoblastic leukemia (T-ALL)." (PMID 39408811, 2024). "A total of 45%–48% of B cell precursor acute lymphoblastic leukemia (BCP-ALL) PDX models contain canonical focal deletions of the tumor suppressors on chromosome 9p, CDKN2A or CDKN2B, the majority of which are homozygous." (PMID 31693904, 2019). "In acute lymphoblastic leukemia (ALL) MDM2 is overexpressed and CDKN2A gene is frequently deleted." (PMID 28018226, 2016).
Obesity (46 papers, 2012 to 2025). Accumulation of substantial excess body fat. "Therapeutically, the expressions of both Cdkn2a and Becn1 are upregulated in obesity and positively associated with adiposity in mice and humans." (PMID 37169793, 2023). "For instance, mice with Cdkn2a gene deficiency were protected against high-fat diet-induced obesity, had higher energy expenditure, and had better insulin sensitivity compared to Cdkn2a-normal mice." (PMID 35055468, 2022). "The locus of the CDKN2A/B on chromosome 9p21 has been widely investigated and showed an association with a higher incidence of coronary artery calcium, ischemic stroke, obesity, T2DM, cardiomyopathy, myocardial infarction, coronary heart disease, and low HDL–cholesterol levels." (PMID 38193570, 2024). "An inverse association between CDKN2A methylation and obesity was found in adipose tissue from adults, suggesting that differential CDKN2A methylation may be a robust marker of adiposity across cord and adipose tissue." (PMID 28473239, 2017). "Adjusting for sex alone did not alter the significant upregulation of GLB1, ZMAT3, CDKN1A, and CDKN2A in individuals with obesity (Sup." (PMID 40127780, 2025). "Mature human adipocytes undergo senescence under obesity and hyperinsulinemia stimulation, exhibiting premature aging transcriptomic and secretory characteristics, including upregulation of CDKN2A, CDKN1A, and CCND1 gene expression, and downregulation of HMGB1 and HMGB2 gene expression." (PMID 39963130, 2025). "The etiology remains elusive, but potential triggers include genetic predisposition, smoking, obesity, hypertension, and immunocompromised status, which may be associated with alterations in the NF2 and CDKN2A genes." (PMID 39850820, 2024). "Understanding how Cdkn2a can relay to initiate a thermogenic program in hiPSC-BAPs is a first step to envisage activating beiging as a new putative therapy to alleviate the effects of obesity and to prevent insulin resistance and T2D." (PMID 36980212, 2023). "We further investigated the correlation between Cdkn2a and Becn1 mRNA levels and obesity." (PMID 37169793, 2023). "We found that loss of Cdkn2a in beige adipocytes results in prolonged beige adipocyte maintenance, enhanced energy expenditure, improved glucose tolerance, and increased resistance to high-fat, high-sucrose (HFHS) diet-induced obesity." (PMID 37169793, 2023). "Hence, blocking Cdkn2a-mediated BECN1 activity holds therapeutic potential to sustain beige adipocytes in treating obesity and related metabolic diseases." (PMID 37169793, 2023). "Interestingly, Cdkn2a expression is increased in adipose tissue of patients with obesity." (PMID 40211057, 2025). "Our findings reveal that Cdkn2a and Becn1 function as potent positive regulators of beige-to-white adipocyte transition, providing a potential therapeutic target for pharmacological intervention to combat the obesity epidemic and its related metabolic diseases." (PMID 37169793, 2023). "Beige adipocytes lacking Cdkn2a exhibit prolonged lifespan, and male mice confer long-term metabolic protection from diet-induced obesity, along with enhanced energy expenditure and improved glucose tolerance." (PMID 37169793, 2023). "Obesity may not have induced CDKN2A hypermethylation at the presymptomatic stage but induced aberrant methylation in later PC development." (PMID 38622664, 2024). "Collectively, our findings unveil insights into the molecular mechanisms by which Cdkn2a regulates beige adipocyte maintenance via BECN1-mediated autophagy and provide a potential therapeutic strategy to lock into a stable beige identity and treat obesity and related metabolic diseases." (PMID 37169793, 2023).
Obesity (continued). "Although GWAS studies do not suggest a link between CDKN2A/B locus SNPs and obesity risk in adult populations, intriguingly, ANRIL may be a genomic site of environmental epigenetic influence on obesity." (PMID 30087655, 2018). "As one pathway to obesity has been suggested to involve fetal undernutrition followed by rapid postnatal weight gain, we used longitudinal measurements of fetal growth from the SWS cohort to derive conditional abdominal growth velocity in late gestation and related this to cord CDKN2A methylation." (PMID 28473239, 2017). "Similar to KRAS and CDKN2A, HFD-induced obesity did not influence methylation levels in these 14 CpGs." (PMID 38622664, 2024).